JADE2 (jade family PHD finger 2)
Description:
Scaffold subunit of some HBO1 complexes, which have a histone H4 acetyltransferase activity. Acts as an E3 ubiquitin-protein ligase mediating the ubiquitination and subsequent proteasomal degradation of target protein histone demethylase KDM1A. Also acts as a ubiquitin ligase E3 toward itself. Positive regulator of neurogenesis (By similarity).
Synonyms: KIAA0239; PHF15; JADE-2
Tractability: PROTAC: ubiquitination databases record sites on it; its protein half-life has been measured.
Gene: Protein-coding gene on chromosome 5 (134,523,979 to 134,583,230, forward strand). Ensembl gene ENSG00000043143.
Subcellular location (Human Protein Atlas): Nucleoplasm
Pathways (Reactome):
Chromatin organization: HATs acetylate histones
Gene Ontology:
Molecular function: histone H3K14 acetyltransferase activity; histone H4K12 acetyltransferase activity; histone H4K16 acetyltransferase activity; histone H4K5 acetyltransferase activity; histone H4K8 acetyltransferase activity; protein binding; ubiquitin protein ligase activity; histone reader activity
Biological process: regulation of cell cycle; regulation of DNA biosynthetic process; regulation of DNA replication; chromatin organization; chromatin remodeling; protein ubiquitination
Cellular component: extracellular exosome; histone acetyltransferase complex; nucleoplasm
Genetic constraint (gnomAD): Loss-of-function variants: 12 observed, 77.82 expected, observed/expected ratio (o/e) 0.15, 90% interval 0.098 to 0.25. The upper end of that interval is the gene's LOEUF score, 0.25, which puts it in group 1 of 6, group 1 being the genes least tolerant of losing a copy. Missense variants: 827 observed, 1,119.7 expected, observed/expected ratio (o/e) 0.74, 90% interval 0.7 to 0.78. Synonymous variants: 434 observed, 461.33 expected, observed/expected ratio (o/e) 0.94, 90% interval 0.87 to 1.02.
Homologues: Orthologues: chimpanzee JADE2 (99% identical), macaque JADE2 (99% identical), dog JADE2 (93% identical), guinea pig JADE2 (92% identical), rabbit JADE2 (92% identical), mouse Jade2 (91% identical), rat Jade2 (90% identical), pig JADE2 (89% identical), tropical clawed frog jade2 (62% identical), zebrafish jade2 (53% identical), Drosophila melanogaster Br140 (22% identical), Caenorhabditis elegans phf-15 (19% identical), and 1 more. Paralogues in human: JADE1 (46% identical), JADE3 (38% identical), BRPF3 (24% identical), BRD1 (23% identical), BRPF1 (23% identical), PHF14 (17% identical), MLLT10 (16% identical), MLLT6 (16% identical).
Diseases named in the same sentence as JADE2 in open-access papers:
JADE2 is named in the same sentence as 14 diseases in open-access papers, as found by Europe PMC text mining. Sharing a sentence is not in itself a finding about the gene and the disease. The quoted sentences say what the papers report.
ovarian carcinoma (3 papers, 2021 to 2023). A malignant neoplasm originating from the surface ovarian epithelium. "In ovarian cancer, JADE2 has been shown to be highly overexpressed and may function to regulate YAP1 a critical ovarian cancer oncogene, whilst a gene fusion between JADE2 and NUP98 has been observed in a pediatric acute myeloid leukemia." (PMID 37761019, 2023). "Studies have shown that KAT7 enhances the mechanical transduction pathway and membrane elasticity of ovarian cancer cells through the overexpression of preferential acetylation histone H4 of co-mediator JADE2, thus improving the migration ability and invasiveness of ovarian cancer cells." (PMID 36172179, 2022).
lung carcinoma (2 papers, 2022 to 2023). "We identified three genetic variants significantly associated with lung cancer risk: rs329118 in JADE2 (P = 8.80E−09), rs2285521 in GGA2 (P = 4.43E−08), and rs198459 in MYRF (P = 1.60E−06)." (PMID 35773316, 2022). "As such, in this manuscript, we set out to assess the expression of JADE2 in NSCLC to determine if its expression also had any potential utility as a biomarker in lung cancer at both the mRNA and protein levels." (PMID 37761019, 2023).
non-small cell lung carcinoma (2 papers, 2023 to 2024). A group of at least three distinct histological types of lung cancer, including non-small cell squamous cell carcinoma, adenocarcinoma, and large cell carcinoma. "Findings on non-small cell lung cancer (NSCLC) reveal that JADE2’s heightened expression correlates with improved 5-year survival rates, underscoring its role in tumorigenesis." (PMID 38813086, 2024). "Using a series of standard biological and bioinformatics approaches we investigated JADE2 expression in surgically resected non-small cell lung cancer (NSCLC) for both mRNA and protein to examine for correlations between JADE2 expression and overall survival." (PMID 37761019, 2023).
Hyperglycemia (1 paper, 2020). An increased concentration of glucose in the blood. "Based on human GWAS, SGCD, which is a component of the sarcoglycan complex, and JADE2, which acts as an E3 ubiquitin ligase, were suggested as candidate genes for impaired insulin secretion and hyperglycemia in the R2 congenic region (segment B)." (PMID 32703163, 2020).
neuroblastoma (1 paper, 2024). Neuroblastoma (NB) is the most common solid, extracranial childhood tumor. "RNA sequencing results showed a synergistic induction of genes associated with RA signaling (RARB, RARG), neuronal differentiation (HOXC5, PBX1), and chromatin remodeling (RYBP, JADE2), which are positively correlated with favorable prognosis in neuroblastoma." (PMID 39711563, 2024).
Obesity (1 paper, 2018). Accumulation of substantial excess body fat. "The functions of NUCKS1, JADE2 and LOC107986451 in obesity are unknown, and need to explore in the future." (PMID 29966015, 2018).
renal carcinoma (1 paper, 2023). A carcinoma arising from the epithelium of the renal parenchyma or the renal pelvis. "As another member of the JADE family JADE1 has been linked to renal cancer pathogenesis through a VHL-mutation-dependent mechanism, we next sought to determine if JADE2 mRNA was also associated with mutation of key oncogenic driver mutations in NSCLC such as KRAS or ALK." (PMID 37761019, 2023).
tumor (3 papers, 2013 to 2023). "Correlations between JADE2 expression and various parameters such as tumor mutational burden and immune cell infiltration are explored." (PMID 37761019, 2023). "Links between JADE2 mRNA expression and a number of mutated genes were identified, and associations between JADE2 expression and tumor mutational burden and immune cell infiltration were explored." (PMID 37761019, 2023). "We then assessed the expression of JADE2 mRNA in a panel of surgically resected fresh frozen normal/tumor-matched patient samples by qPCR." (PMID 37761019, 2023). "When GTEx normal samples were included, the mRNA for JADE2 was shown to be not significantly altered between tumor and normal in both LUAD and LUSC which correlates with that observed for the cProSite protein data." (PMID 37761019, 2023).
cancer (2 papers, 2022 to 2023). A tumor composed of atypical neoplastic, often pleomorphic cells that invade other tissues. "Given the recent link identified between JADE2 and NSCLC cancer risk, we decided to focus on this member of the JADE family in NSCLC." (PMID 37761019, 2023). "Several areas of investigation will be required moving forwards to critically delineate the potential roles of JADE2 in cancer." (PMID 37761019, 2023). "Results from other studies collected in the cancer microarray database Oncomine also provided evidence for a higher expression level of JADE2 in NSCLC tissue (both LUAD and LUSC) than in normal lung tissue." (PMID 35773316, 2022). "JADE family members, and in particular JADE2 have not been studied in any great detail in cancer." (PMID 37761019, 2023).
JADE2 also shares sentences with these, for which no sentence is quoted: acute myeloid leukemia (1 paper); androgenetic alopecia (1); Anorexia (1); glioblastoma (1); kidney cancer (1).